HMGB1 (high mobility group box 1)
Diseases named in the same sentence as HMGB1 in open-access papers (continued):
Sharing a sentence is not in itself a finding about the gene and the disease.
diabetes (continued). "Based on the potential role of HMGB1 in the pathogenesis of diabetes, It was presumed that HMGB1 inhibitors would probably affect the diabetes onset." (PMID 30410469, 2018). "For example, administration of anti-HMGB1 antibody reduced the diabetes incidence and delayed the onset of diabetes in NOD mice." (PMID 30410469, 2018). "High mobility group protein B1 (HMGB1) is a RAGE (also known as AGER) agonist whose levels are increased in diabetes and that contributes to pain by modulating peripheral inflammatory responses." (PMID 29930087, 2018). "RAGE is a type I transmembrane protein and a member of the immunoglobulin superfamily, it is increasingly expressed when potential ligands such as HMGB1 or inflammatory mediators are expressed, e.g., in cardiovascular disease, diabetes, and cancer." (PMID 29375570, 2017). "Particularly a recent study showed that serum HMGB-1 is positively related to HbA1c level and is an independent predictor for coronary artery disease in patients with diabetes." (PMID 28789654, 2017). "Our results demonstrate for the first time that LPLI has potent protective effects against inflammation and apoptosis in diabetes-induced SMGs via its suppression of HMGB1/AGE/RAGE, which in turn inhibits the NF-κB pathway." (PMID 28099448, 2017). "HMGB-1 has been shown be an inflammatory mediator promoting chronic inflammation and neovascularization in diabetes." (PMID 28789654, 2017). "The current study is the first to investigate the role of HMGB1/AGE/RAGE in SMGs from diabetic rats and to characterize the underlying mechanism of diabetes complications in that tissue." (PMID 28099448, 2017). "Taken together, our data suggest that LPLI reduces diabetes-induced inflammation by reducing the induction of HMGB1, ultimately leading to inhibition of apoptosis in submandibular glands of diabetic rats." (PMID 28099448, 2017). "Though several drugs were shown to prevent diabetic complications via targeting HMGB-1, much further research is needed to explore novel HMGB-1-targeted therapeutics in diabetes care." (PMID 27847406, 2016). "We previously found that glycyrrhizin inhibited HMGB-1 expression in AGEs-induced EPCs, indicating the possible effect of glycyrrhizin in EPCs dysfunction in diabetes." (PMID 27847406, 2016). "In the current study, the i.p. injection of STZ induced diabetic neuropathic pain model in rats, as well as increased CaMKIV phosphorylation and HMGB1 expression levels in DRG neurons." (PMID 27216039, 2016). "The HMGB1/RAGE/NF-ΚB pathway is closely associated with inflammation in many diseases, such as systemic lupus erythematosus, diabetes, etc.." (PMID 27026909, 2016). "The current results demonstrate that intrathecal administration of KN93, attenuates STZ-induced diabetic neuropathic pain, CaMKIV phosphorylation level, and HMGB1 expression level in DRG." (PMID 27216039, 2016). "The present study investigated the effects of CaMKIV on diabetic neuropathic pain, as well as the relationship of CaMKIV with HMGB1 expression in dorsal root ganglion (DRG)." (PMID 27216039, 2016). "In the present study, we show that PCE effectively prevented the diabetes-induced upregulation of the expression of HMGB1 and RAGE and NF-κB in the retina." (PMID 26950148, 2016). "Following a single dose of 200 and 400 ng HMGB1, wound closure was accelerated in diabetes mice compared to wounds treated either with saline or 800 ng of this protein." (PMID 27886093, 2016). "This review will give an overview of recent advances in HMGB-1 in diabetes, diabetic cardiovascular complications, diabetic nephropathy (DN), and diabetic retinopathy (DR), and then we will focus on therapeutic strategies targeting HMGB-1." (PMID 27847406, 2016). "The results of the present study, together with the previous findings, indicate that HMGB-1 is not only an effector of oxidative stress, but also an inducer of oxidative stress in diabetes-induced late EPCs." (PMID 26798412, 2016).
diabetes (continued). "Diabetes induces HMGB-1 expression in various cells via oxidative stress; however, elevated HMGB-1 promoted initiation and development of diabetes via induction of insulin deficiency and insulin resistance." (PMID 27847406, 2016). "Recently, cytoplasmic translocation of HMGB-1 was found in diabetes and high-glucose-induced retinal pericytes, which was dependent on RAGE/NF-κB pathway." (PMID 27847406, 2016). "In this study, we have shown that diabetes enhances the increase in HMGB1 serum levels and expression of the inflammatory cytokines IL-1β, IL-6, and inflammation-related enzyme after cerebral I/R injury in mice." (PMID 27596007, 2016). "In this review, we focus on the role of HMGB-1 in diabetes-related complications and the therapeutic strategies targeting HMGB-1 in diabetic complications." (PMID 27847406, 2016). "The high mobility group box 1 (HMGB1) protein mediates the cardiomyocyte–cardiac fibroblast interaction that contributes to induction of myocardial fibrosis in diabetes mellitus (DM)." (PMID 27821807, 2016). "Since HMGB-1 was involved in diabetes, some HMGB-1-targeted therapeutic strategies were found to intervene in diabetic complications." (PMID 27847406, 2016). "The results indicated that CaMKIV is involved in STZ-induced diabetic neuropathic pain via regulation of HMGB1." (PMID 27216039, 2016). "HMGB-1-RAGE interaction promotes islet cell apoptosis in diabetes by inducing oxidative stress, contributing to insulin deficiency." (PMID 27847406, 2016). "Increasing evidence has summarized the contribution of HMGB-1 to coronary artery disease with diabetes." (PMID 27847406, 2016). "Recently, we have previously found that HMGB-1 was involved in diabetes-induced oxidative stress in endothelial progenitor cells." (PMID 27833703, 2016). "AGEs were used to establish an in vitro diabetes model to investigate the role of HMGB-1 in diabetes-induced oxidative stress." (PMID 26798412, 2016). "This is in agreement with previous findings that diabetes promotes both the elevation of HMGB1 expression and a poor outcome after ischemic stroke in rats." (PMID 27596007, 2016). "In line with our studies, Feng and colleagues indicated that the interaction of HMGB-1 and its receptors triggered the oxidative stress in endothelial dysfunction; similarly, serum HMGB-1 concentration was shown to reflect endothelial dysfunction in diabetes." (PMID 27847406, 2016). "The activation of HMGB1/RAGE is an important signaling pathway that is involved in the initiation of the pro-inflammatory pathways that play important roles in diabetes-induced retinopathy." (PMID 26950148, 2016). "In this study, we investigated the role of high mobility group box-1 (HMGB-1) in diabetes-induced oxidative stress." (PMID 26798412, 2016). "Multivariate logistic regression analyze revealed that plasma HMGB1 levels were significantly correlated with diabetes even after controlling for age, sex, blood pressure, lipid profile, Cre and BMI." (PMID 26317615, 2015). "Our previous studies showed that diabetes upregulates HMGB1 expression in the vitreous fluid and preretinal membranes from patients with PDR and its expression correlated with the activity of the disease and the levels of inflammatory biomarkers." (PMID 24733965, 2014). "The HMGB1 inhibitor GA attenuated diabetes-induced upregulation of HMGB1 protein and mRNA; cleaved caspase-3 and glutamate; and downregulation of synaptophysin, TH, GS, and GLO1 in the retinas of rats." (PMID 24733965, 2014). "Constant GA intake from the onset of diabetes significantly attenuated diabetes-induced upregulation of HMGB1, ERK1/2 activation, and cleaved caspase-3 by about 73%, 55%, and 78%, respectively." (PMID 24733965, 2014). "Taken together, these findings suggest that HMGB1 contributes to retinal neuropathy induced by diabetes." (PMID 24733965, 2014). "Recently, we verified that HMGB1 promoted diabetes-induced myocardial fibrosis and heart dysfunction." (PMID 25210949, 2014).
diabetes (continued). "Western blot analysis was used to assess the effect of GA on diabetes-induced alterations of HMGB1, ERK1/2 activation, cleaved caspase-3, synaptophysin, TH, GS, and GLO1." (PMID 24733965, 2014). "In vivo, cardiac phospho-Ets-1 (Thr38) level was significantly increased in diabetic mice, HMGB1 inhibition reduced diabetes-induced activated Ets-1." (PMID 25210949, 2014). "The HMGB1 inhibitor GA attenuated diabetes-induced upregulation of HMGB1 and diabetes-induced retinal neuropathy." (PMID 24733965, 2014). "In the present study, we investigated the pathological role of HMGB1 in diabetes-induced retinal neuropathy." (PMID 24733965, 2014). "GA intake significantly attenuated diabetes-induced upregulation of HMGB1 mRNA by about 3.5-fold compared to untreated diabetic rats." (PMID 24733965, 2014). "In conclusion, our data point to a potential novel and pivotal role for HMGB1 as a mediator of diabetes-induced neuropathy in the retina." (PMID 24733965, 2014). "To delineate the role of HMGB1 in diabetes-induced myocardial apoptosis, we silenced HMGB1 gene expression in myocardia of diabetic mice." (PMID 25210949, 2014). "We also showed that the HMGB1 inhibitor GA was effective in preventing diabetes-induced NF-κB activation." (PMID 24733965, 2014). "Our findings suggest that diabetes-induced decrease of BDNF in the retina seems to be mediated by HMGB1." (PMID 23766563, 2013). "In a previous study, we demonstrated that constant GA intake from the onset of diabetes significantly attenuated diabetes-induced upregulation of HMGB1 in the retinas of rats." (PMID 23766563, 2013). "BDNF was significantly downregulated in the serum from patients with PDR and in the retinas of rats with diabetes, whereas HMGB1 was significantly upregulated." (PMID 23766563, 2013). "It has been reported that a single injection with neutralizing anti-HMGB1 antibody into spinal cord attenuated diabetes-induced hypersensitivity in mice." (PMID 23991202, 2013). "The effect of the HMGB1 inhibitor glycyrrhizin on diabetes-induced changes in retinal BDNF expressions was studied." (PMID 23766563, 2013). "Diabetes exacerbates systemic inflammation as evidenced by higher serum HMGB1 in the rat systemic inflammation model." (PMID 23414442, 2013). "Activation of HMGB1/RAGE signaling axis is important in promoting proinflammatory pathways considered to play an important role in diabetes-induced retinal neuroinflammation." (PMID 23766563, 2013). "Diabetes and intravitreal administration of HMGB1 induced significant upregulation of the expression of HMGB1, TBARS, and cleaved caspase-3, whereas the expression of BDNF and synaptophysin was significantly downregulated in rat retinas." (PMID 23766563, 2013). "A reduced tissue inflammation was also confirmed by the decreased inflammatory cell infiltration and lower expression of HMGB-1 in the ventricular myocardium, after 8 weeks of diabetes." (PMID 22768138, 2012). "The decrease in HMGB-1 expression in treated animals after 8 weeks of diabetes (D8R) is allegedly due to the RSV-induced reduction of both cardiac cell death and recruitment of inflammatory cells." (PMID 22768138, 2012). "Larger studies are needed to ascertain more definitely the role of HMGB1 in the development of vascular complications in diabetes." (PMID 22752054, 2012). "Activation of HMGB1/RAGE signaling axis is important in promoting proinflammatory pathways considered to play an important role in diabetes-induced retinal vascular inflammation." (PMID 23118492, 2012). "Activation of the HMGB1/RAGE signaling axis is important in promoting proinflammatory pathways which are considered to play an important role in diabetes-induced retinal vascular inflammation." (PMID 21365018, 2011). "Previous work has suggested that PANoptosis may exacerbate diabetes by promoting inflammation through the release of intracellular danger signals such as HMGB1 and ATP." (PMID 41008530, 2025).
diabetes (continued). "Following adjustment for age, smoking history, hypertension, hyperlipidemia,statin use and diabetes, the serum levels of HMGB1 (OR: 1.212, 95% CI:1.003–1.465, p < 0.05) and HMGB2 (OR: 1.117, 95% CI: 1.005–1.241,p < 0.05) were independently associated with AAA rupture." (PMID 40776964, 2025). "Furthermore, we intend to explore HMGB-1 antagonism as a plausible pharmacological target for the management of diabetes complications." (PMID 39271468, 2024). "As recent study revealed that inhibition of microglial HMGB1 release prevented neuroinflammation and protected hippocampal neuronal from type 2 diabetes mellitus, suggesting that microglia-derived HMGB1 functions as a pivotal mediator in modulating neurotoxic and pro-inflammatory activities." (PMID 38515139, 2024). "The elevated expression level of HMGB1 in diabetic retinas is reported to be repressed by the activation of SIRT1, thereby alleviating the retinal endothelial barrier dysfunction caused by diabetes." (PMID 38438663, 2024). "Polyclonal anti-HMGB1 antibodies have also been implicated in neuropathic pain relief, reduction in neuronal degeneration, downregulation of pro-inflammatory TNF-α, and the restoration of glycemic control in diabetes." (PMID 39682695, 2024). "RSV significantly reduced the downregulation of occluding induced by diabetes and upregulation of high-mobility group box-1 (HMGB1), induced by diabetes, as well as the receptor for advanced glycation end (RAGE) products and breakdown of blood-retinal barrier (BRB) in the diabetic retina." (PMID 38716357, 2024). "Liu showed that by downregulating HMGB1 levels and inhibiting NF-κBp65 phosphorylation, the drug was able to improve the diabetes-induced reductions in diastolic and systolic cardiac systolic function and conduction abnormalities and alleviate cardiac insufficiency in diabetic heart disease." (PMID 37065747, 2023). "However, both Rilmenidine-treated groups showed decreased HMGB-1 levels: diabetes + 0.1 mg/kg Rilmenidine group (5.3 ± 0.08 pg/mg) and diabetes + 0.2 mg/kg Rilmenidine group (5.2 ± 0.1 pg/mg)." (PMID 38055406, 2023). "Our interest in HMGB1 stemmed from its established upregulation in diabetes." (PMID 36982926, 2023). "Autophagy and HMGB1 play important roles in diabetes and its complications." (PMID 37065747, 2023). "In addition, serum levels of the high mobility group, box 1 (HMGB1) protein are elevated in patients with diabetes." (PMID 37242739, 2023). "Moreover, researchers have constructed diabetic rat models and found that diabetes increases HMGB1 levels, which are reduced when the HMGB1 inhibitor glycyrrhizin is administered, and apoptosis, inflammatory responses and retinopathy are reduced." (PMID 37065747, 2023). "Our previous study indicated that glycyrrhizin acid (GA) could protect against endothelium-dependent relaxation in an animal model of diabetes and attenuate neointimal formation by inhibiting HMGB1 in a rabbit vascular injury model." (PMID 37266147, 2023). "Studies have shown that IL-1β-induced pancreatic β cell death and HMGB1 release may lead to the onset of diabetes." (PMID 37065747, 2023). "HMGB1 is an endogenous DAMP known to be upregulated in the serum of patients with diabetes." (PMID 36982926, 2023). "Studies have shown that HMGB1 plays an important role in insulin resistance and diabetes." (PMID 37065747, 2023). "In addition, the HMGB1‐RAGE pathway is known to be involved in various inflammatory diseases (diabetes, rheumatoid arthritis, inflammatory kidney disease, heart disease, tumor growth, chronic obstructive pulmonary disease)." (PMID 37337402, 2023). "The suppression of HMGB1 significantly inhibited the progression of diabetes in mice." (PMID 37667233, 2023). "Intervening in HMGB1 or other autophagy targets and exploring their mechanisms are of great theoretical importance and have clinical applications for the prevention and treatment of diabetes and its complications." (PMID 37065747, 2023).
diabetes (continued). "Such inhibition of diabetes-driven activation of HMGB1 by Fer-1 coincided with the reduction of all the examined ferroptosis events in the liver, strongly suggesting the involvement of HMGB1 in the regulation of diabetes-induced liver ferroptosis." (PMID 36012572, 2022). "Thus, diabetes is accompanied by increases in serum high mobility group box-1 (HMGB1), an endogenous molecule known to function as a DAMP to activate TLRs, such as TLR4." (PMID 36499260, 2022). "Our study shows that HMGB1 released from Schwann cells in diabetes milieu may promote neuroinflammation in DPN via excessive activation of RAGE/p38MAPK/NF-κBp65 pathways." (PMID 35578754, 2022). "Multivariate logistic regression analysis showed that diabetes, smoking, regular postoperative medication, increased fibrinogen, decreased red blood cells, increased hs-CRP, and increased postoperative HMGB1 were independently associated with postoperative restenosis in patients with LEASO." (PMID 36704514, 2022). "In addition, HMGB1 plays a critical role in diabetes‐related dysfunctions of bone marrow stromal cells (BMSCs) and impaired osteointegration." (PMID 35706377, 2022). "The results showed that diabetes, smoking, increased fibrinogen, decreased red blood cells, elevated hs-CRP, and increased postoperative HMGB1 were independent risk factors for postoperative restenosis in patients with LEASO, while regular postoperative medication was a protective risk factor." (PMID 36704514, 2022). "Also, in the “mild-course” COVID-19 group patients with diabetes mellitus were overrepresented (50%) and HMGB1 levels are known to be increased in diabetes mellitus." (PMID 36251689, 2022). "In that context, HMGB1 has been recognized as important in controlling the fate of liver cells as well as in determining the type of cell death (apoptosis or autophagy) in the progression of liver damage in diabetes." (PMID 36012572, 2022). "Whether this HMGB1/RAGE/NF-κB cascade involves in the disturbed oral wound healing in diabetes remains to be determined." (PMID 34573077, 2021). "High‐mobility group box‐1 (HMGB‐1), a highly conserved nuclear protein, can be translocated into the cytoplasma and released into extracellular space under particular conditions, such as diabetes and inflammation." (PMID 33724642, 2021). "Taken together with the previous finding that HMGB‐1 mediates high‐glucose‐induced calcification in vascular smooth muscle cells (VSMCs) of saphenous veins, it has still remained elusive whether HMGB‐1 could link diabetes with vascular calcification." (PMID 33724642, 2021). "The promotion of HMGB1 secretion by glycation suggests that a glycation-promoting condition, such as diabetes, might increase the extracellular HMGB1 levels." (PMID 34068442, 2021). "However, inhibition of HMGB‐1 or ERS reversed the effects of diabetes on vascular calcification, as demonstrated by the findings that these mRNA expressions were attenuated by treatment with Gly or 4‐PBA." (PMID 33724642, 2021). "Thus, diabetes induced translocation and secretion of HMGB‐1 via ERS, which resulted in calcification in diabetic mice and in AGEs‐treated VSMCs." (PMID 33724642, 2021). "High‐mobility group box‐1 (HMGB‐1) plays a substantial role in diabetes and its complications." (PMID 33724642, 2021). "Our previous studies demonstrated that HMGB1 can be either passively released from damaged pancreatic beta cells or actively secreted by islet-infiltrating immunocytes such as dendritic cells (DCs) and macrophages, and that blockade of HMGB1 in 8- or 12-week-old NOD mice delayed diabetes onset." (PMID 32072192, 2020). "The levels of immunostaining to HMGB-1 in retinas were significantly higher in the diabetic rats than in the normal ones, and Cs-A treatment significantly reduced this effect induced by diabetes." (PMID 32019593, 2020).